USH2A (usherin)
Diseases named in the same sentence as USH2A in open-access papers (continued):
Sharing a sentence is not in itself a finding about the gene and the disease.
Usher syndrome type 2A (26 papers, 2011 to 2025). Any Usher syndrome in which the cause of the disease is a mutation in the USH2A gene. "This variant was encountered in 0.9% of mutant alleles of the USH2A gene in Dutch and Swedish patients with Usher syndrome type IIa, which is significantly lower than in Russia (χ2 = 26, p < 0.001)." (PMID 39596236, 2024). "Biallelic pathogenic variants in USH2A contribute significantly to the proportion of patients with IRDs worldwide, causing Usher syndrome type IIA and non-syndromic RP." (PMID 37337429, 2023). "Mutations in the USH2A gene (MIM: 608400) cause autosomal recessive retinitis pigmentosa (RP) (MIM: 613809) or Usher syndrome type IIA (MIM: 276901), a disorder resulting in congenital sensorineural hearing loss and RP." (PMID 37337429, 2023). "In this study, we report a case carrying novel biallelic variants in USH2A causing progressive early adolescent onset visual and hearing impairment consistent with Usher Syndrome Type IIA." (PMID 35346118, 2022). "We report a case carrying novel biallelic variants in USH2A causing progressive early adolescent onset visual and hearing impairment consistent with Usher Syndrome Type IIA." (PMID 35346118, 2022). "This variant removed all functional domains and elucidated the genetic roles of the USH2A mutant allele in this family inflicted with Usher syndrome type IIA." (PMID 32449591, 2020). "In conclusion, we have successfully identified a rare homozygous frameshift variant c.99_100insT (p.Arg34Serfs*41) with maternal UPD in the USH2A gene, which would cause Usher syndrome type IIA in our Chinese family." (PMID 32449591, 2020). "In 1998, three biologically important variants (c.2299del, c.2898del, and c.4336_4337del) in the USH2A gene were reported to be responsible for the autosomal recessive disorder, Usher syndrome type IIA (USH2A, MIM #276901), featured by sensorineural hearing impairment and progressive RP." (PMID 36875754, 2023). "Thus, our studies indicate that the USH2A pathogenic, homozygous variant c.99_100insT (p.Arg34Serfs*41) should cause Usher syndrome type IIA in the proband in this Chinese family." (PMID 32449591, 2020). "However, it remains unknown why some mutations in USH2A result in Usher syndrome type IIa, while others develop nonsyndromic RP." (PMID 32893482, 2020). "Mutations in Usher syndrome 2A (USH2A; OMIM 608400) are a considerable cause of RP and can result in two distinct phenotypes: nonsyndromic RP and Usher syndrome type IIa." (PMID 32893482, 2020). "Presumed nonpathogenic variants of the Usher syndrome type IIA (USH2A) gene found in this study." (PMID 21686329, 2011).
retinal disease (22 papers, 2015 to 2025). "Moosajee and colleagues have generated episomal plasmid vectors containing the coding region of the very large USH2A gene, a common cause of the retinal disease retinitis pigmentosa." (PMID 37337429, 2023). "A subset of patients was screened for mutations in retinal disease genes, and mutations in the following genes were found: three cases with USH2A; three cases with EYS; one case each with USH3A (CLRN1), DHX38, RHO, RPGR, and RP9." (PMID 33037922, 2021). "Lenassi and colleagues have proposed a model of an allelic hierarchy, where the presence of at least one retinal disease specific USH2A allele results in the preservation of normal hearing and leads to nsRP." (PMID 33121974, 2020). "In family RP-0605, re-analysis with NGS uncovered the presence of two coexisting retinal diseases (RP and cone affectation), since biallelic pathogenic variants in two different RD-related genes (USH2A and CNGB3) have been identified." (PMID 29912909, 2018). "Allelic heterogeneity, with different mutations in the same gene causing different phenotypes, is evident also in USH2A-related retinal disease." (PMID 28127548, 2016). "We have shown that an allelic hierarchy of variants affecting USH2A function is likely with ‘retinal disease-specific' alleles being phenotypically dominant to ‘Usher syndrome type II' alleles." (PMID 25649381, 2015). "The mutations are distributed across 21 retinal disease genes with USH2A as the most frequently mutated gene, accounting for 11 solved cases (22%)." (PMID 26667666, 2015). "USH2A is the second most common gene affected in inherited retinal disease, accounting for approximately 8% of IRDs22." (PMID 39922978, 2025). "Gene augmentation is a valuable therapeutic strategy for treating many inherited retinal diseases; however, conventional adeno-associated virus (AAV) gene therapy cannot accommodate cDNAs exceeding 4.7 kb, such as the 15.6-kb-long USH2A coding sequence." (PMID 37337429, 2023). "In the present study, all patients diagnosed as USH2 carried a null USH2A variant in compound heterozygous state with p.(Cys759Phe), being the former variant allegedly confined to retinal disease." (PMID 29912909, 2018). "In addition, R-loops were identified in 20 genes involved in retinal disease including Ush2a, Pcdh15, and Abcc6." (PMID 39345562, 2025). "In addition to USH2A variants, mutations in PDZD7 gene (PDZ domain-containing 7) have been proposed to act as a retinal disease modifier in USH2A patients, explaining the frequently observed variability of the visual phenotype." (PMID 33121974, 2020).
Retinal dystrophy (16 papers, 2015 to 2025). Retinal dystrophy is an abnormality of the retina associated with a hereditary process. "Our study revealed a prevalence of 21% of exon 13 variants for USH2A-related retinal dystrophies in Taiwanese, which is relatively high compared with those in previous studies." (PMID 38879497, 2024). "Only a few studies have focused on USH2A-associated retinal dystrophies in Taiwan." (PMID 38879497, 2024). "However, few studies on USH2A-associated retinal dystrophies have been conducted in the Taiwanese population." (PMID 38879497, 2024). "Considering that USH2A-related retinal dystrophies have a rather late onset, the earlier we can detect this gene in patients, the sooner potential gene therapy can be initiated." (PMID 38879497, 2024). "This study provided a deeper understanding of the detailed clinical features using multimodal imaging, genetic spectrum, and genotype–phenotype correlations of USH2A-related retinal dystrophies in Taiwan." (PMID 38879497, 2024). "In this study, we aimed to investigate the detailed clinical features, genetic spectrum, and genotype–phenotype correlations of USH2A-related retinal dystrophies in Taiwan." (PMID 38879497, 2024). "USH2A was the most frequent gene associated with RP, RDH12 early-onset severe retinal dystrophy, ABCA4 Stargardt disease, PROM1 cone-rod dystrophy, and BEST1 macular dystrophy." (PMID 37217489, 2023). "We focused on USH2A-related retinal dystrophies, a form of arRP." (PMID 38879497, 2024). "Studies have reported that USH2A, EYS and CRB1 are the top three genes responsible for inherited retinal dystrophy." (PMID 34977041, 2021). "A previous study showed that USH2A, EYS, and CRB1 were the top three genes contributing to inherited retinal dystrophy in Chinese patients." (PMID 31269016, 2019). "In another family with 3 affected individuals and 1 presumed non-penetrant member, NGS identified three retinal dystrophy genes (PRPF8, PRPH2 and USH2A) with dis-ease-causing variants in varying combinations among the affected individuals." (PMID 40426944, 2025). "To date, proof‐of‐concept of AONs has been shown in both cell‐based models and animal models for four retinal dystrophy genes: CEP290, CHM (Garanto, van der Velde‐Visser, Cremers, & Collin, 2018), RHO, and USH2A, and represents a promising therapy for retinal dystrophies." (PMID 30950243, 2019). "In addition to CEP290, several other of the most frequently mutated inherited retinal dystrophy genes, e.g., ABCA4, EYS, and USH2A have a cDNA size way exceeding this limit and hence are not amenable for AAV-based gene therapy." (PMID 26325627, 2015).
ciliopathy (10 papers, 2015 to 2024). A genetic disorder of the cellular cilia or the cilia anchoring structures, the basal bodies, or of ciliary function. "Ninein-like protein (NINL) is known to associate with this motor complex and is an important interaction partner of the ciliopathy-associated proteins lebercilin, USH2A and CC2D2A." (PMID 26485514, 2015). "NINL, an important interaction partner of three ciliopathy-associated proteins (lebercilin, USH2A and CC2D2A), was previously shown to associate with this motor complex." (PMID 26485514, 2015). "This ciliopathy caused by various mutations of the usherin gene leads to vision and hearing loss." (PMID 38541998, 2024). "In addition, among of our cohort of 18 ciliopathy patients, 9 had USH2A mutations, and this can cause an impressive rate of progression." (PMID 31370859, 2019). "Although there could be variability in severity, preliminary analyses of the rates of vision loss suggested that EYS is a more rapidly progressive disease than other ciliopathies causing arRP, such as USH2A and MAK." (PMID 28704921, 2017). "For instance, 3 of 11 ciliopathy-like patients carried heterozygous pathogenic variants in ciliopathy genes, such as ALSM1, USH2A, and WDPCP, thus it might support the initial clinical suspicion." (PMID 29588463, 2018). "From the data at hand in these three ciliopathies, it can be suggested that EYS peripheral disease progression is faster than that of the MAK and USH2A phenotypes." (PMID 28704921, 2017). "NINL has been previously shown to bind several other ciliopathy proteins present at the base of cilia, specifically LCA5 and USH2A, suggesting that it may play a more pivotal role in vesicular trafficking in photoreceptors than CC2D2A." (PMID 26485645, 2015).
Stargardt disease (9 papers, 2019 to 2025). "USH2A-associated retinal pathology is the third most common autosomal recessive form of IRD among Russian patients, after Stargardt disease, caused by biallelic variants in the ABCA4 gene and achromatopsia, associated with mutations in the CNGB3 gene." (PMID 39596236, 2024). "Several genes, including ABCA4 (Stargardt disease), USH2A (RP and Usher syndrome), and CEP290 (LCA) exceed the AAV’s capacity." (PMID 31284566, 2019). "The other IRD group included Stargardt's disease carrying ABCA4 variants, as well as individuals with Cone-Rod Dystrophy (CORD) or RP presenting with various genetic variants such as RDH12, RPGR, LCA5,CEP290, RP2, USH2A, and EYS." (PMID 38466290, 2024).
Cone rod dystrophy (8 papers, 2011 to 2024). "Amongst the genes causing rod-cone dystrophy, the molecular effect of mutations in RHO, RP1, RP9, PRPH-2 and USH2A have been studied using iPSCs." (PMID 26237613, 2014).
Leber congenital amaurosis (7 papers, 2013 to 2025). Leber congenital amaurosis (LCA) is a retinal dystrophy defined by blindness and responses to electrophysiological stimulation (Ganzfeld electroretinogram (ERG)) below threshold, associated with severe visual impairment within the first year of life. "Moreover, another large gene, CEP290, can be rescued on the mRNA level by antisense oligonucleotides (AONs; QR-110 for Leber congenital amaurosis (LCA), with CEP290; QR-421a for LCA with USH2A)." (PMID 32545533, 2020).
autosomal recessive deafness (5 papers, 2014 to 2024). "In particular, we did not test the most frequently mutated genes in patients with autosomal recessive hearing loss, such as SLC26A4, USH2A, and MYO7A, because their large size would have made Sanger sequencing labour-intensive." (PMID 30344259, 2018).
breast carcinoma (5 papers, 2014 to 2025). "Mutations in USH2A and MUC16, encoding usherin and mucin, rank a distant 3rd and 4th by odds ratio (1.7 and 1.5, respectively), but their roles in breast cancer remain unclear." (PMID 41226361, 2025). "Of the out-of-frame validated chimeras, we identified recurrent expressed chimeric transcripts involving CDK12 (2.7%) and RAE1 (1%), and DNA rearrangements involving C17ORF57 (0.5%), NSF (0.5%), USH2A (0.5%), and LASP1 (1%) from unselected breast cancers in external datasets 12,15–17,41–43." (PMID 24395524, 2014). "CDK12, LASP1, RAE1, C17orf57, NSF, and USH2A were partners of out-of-frame, but not in-frame, fusion genes here and in other massively parallel sequencing analyses of breast cancers 12,15–17,41–43." (PMID 24395524, 2014).
lung adenocarcinoma (5 papers, 2018 to 2025). A carcinoma that arises from the lung and is characterized by the presence of malignant glandular epithelial cells. "In lung adenocarcinoma, the USH2A mutation is one of the most frequently mutated genes for predicting neoantigens." (PMID 34795697, 2021). "Additionally, USH2A mutations have been associated with increased neoantigen loads in lung adenocarcinoma and colon adenocarcinoma." (PMID 40312292, 2025). "On the other hand, USH2A, LRP1B, MUC16, and SYNE1 genes have been reported to have frequently mutated in various cancer types, particularly lung adenocarcinoma and lung squamous cell carcinoma." (PMID 30555633, 2018).
night blindness (5 papers, 2019 to 2024). Inability to see clearly in dim light. "In our study, the ocular phenotypes of patients harboring USH2A variants were consistent with clinical manifestations of RP, which were characterized by progressive night blindness and reduced visual field." (PMID 38245557, 2024). "64% of patients had onset of night blindness after 10 years old, consistent with previous reports that patients with USH2A mutations usually develop RP in the second decade of their life or later." (PMID 36034145, 2022).
sensorineural hearing loss (5 papers, 2014 to 2024). "Pathogenic variants affecting usherin protein cause failure in stereocilia formation and long-term maintenance of photoreceptors, resulting in sensorineural deafness and visual impairment, the main hallmarks of USH." (PMID 39044131, 2024).
achromatopsia (3 papers, 2013 to 2024). Achromatopsia (ACHM) is a rare autosomal recessive retinal disorder characterized by color blindness, nystagmus, photophobia, and severely reduced visual acuity due to the absence or impairment of cone function. "Variants found in both genes (USH2A and CNGB3) segregated in the family; therefore suggesting a RP diagnosis due to USH2A, and a likely cone dystrophy/achromatopsia diagnosis due to CNGB3 in the proband; and a cone dystrophy/achromatopsia diagnosis in his brother (sibling II:2)." (PMID 29912909, 2018).
myopia (3 papers, 2018 to 2025). "Among these ocular disease related or direct high myopia related genes, five genes (CSMD1, HSPG2, RPGR, SEMA4A and USH2A) have pathogenic variants in multiple patients." (PMID 30245926, 2018). "In addition to the novel mutations found in five known myopia genes (ADAMTS18, CSMD1, P3H2, RPGR, and SLC39A5), we also identified pathogenic variants in seven ocular disease genes (ABCA4, CEP290, HSPG2, PCDH15, SAG, SEMA4A, and USH2A) as novel candidate genes." (PMID 30245926, 2018).
autism (2 papers, 2013 to 2024). Persistent deficits in social interaction and communication and interaction as well as a markedly restricted repertoire of activity and interest as well as repetitive patterns of behavior. "Moreover, a deletion encompassing the USH2A gene was found in a patient with autism and speech delay." (PMID 38891944, 2024).
keratoconus (2 papers, 2021 to 2025). A degenerative, structural disorder of the eye, characterized by a cone-shaped protrusion of the cornea. "We performed direct Sanger sequencing and co-segregation analysis of the USH2A gene to identify disease causing variants in a non-syndromic RP family, two USH2 families and two Keratoconus (KC) families." (PMID 33926394, 2021).
Koolen-de Vries syndrome (2 papers, 2018 to 2021). A chromosomal anomaly characterized by developmental delay, childhood hypotonia, facial dysmorphism, and a friendly/amiable behavior. "Notably, clinical refinement of complex phenotypes was achieved in 4 cases, including 2 de novo OTX2-related syndromes, a novel phenotypic association for the ciliary CEP41 gene, and the co-existence of biallelic USH2A variants and a Koolen-de-Vries syndrome–related 17q21.31 microdeletion." (PMID 29588463, 2018).
leukemia (2 papers, 2019 to 2022). A malignant (clonal) hematologic disorder, involving hematopoietic stem cells and characterized by the presence of primitive or atypical myeloid or lymphoid cells in the bone marrow and the blood. "As Ush2a mutations have been shown to play a role in several leukemias and lymphomas, it is possible that this deleterious mutation contributes to the more aggressive phenotype of the transplanted tumors." (PMID 34417556, 2022). "In addition, subclonal mutations in USH2A, a new target shown to be mutated frequently in relapsed leukemia, were significantly associated with dismal clinical outcome in univariate analysis." (PMID 30886153, 2019).
ovarian carcinoma (2 papers, 2020 to 2021). A malignant neoplasm originating from the surface ovarian epithelium. "In addition to that, the function of TTN, CSDM3, RYR2, USH2A and SYNE1 has never been established in ovarian cancer." (PMID 32626534, 2020).
Waardenburg syndrome (2 papers, 2019 to 2023). A disorder characterized by varying degrees of deafness and minor defects in structures arising from neural crest, including pigmentation anomalies of eyes, hair, and skin. "One novel variant in the USH2A gene was detected in one individual, and one novel and one known variant were also detected in the PAX3 and MITF genes, respectively, in two persons with Waardenburg syndrome and profound HL." (PMID 31850270, 2019).
alcohol dependence (1 paper, 2025). Physical and psychological dependence on alcohol. "Ush2a, which was decreased in non-compulsive rats, was found to be associated with alcohol dependence." (PMID 41002437, 2025).
asthma (1 paper, 2024). "Genetic phase contributes to disease risk for gene-trait pairs: ATP2C2-COPD (p = 0.000238), FLG-asthma (p = 0.00205), and USH2A-visual impairment (p = 0.0084)." (PMID 38944039, 2024).
autism spectrum disorder (1 paper, 2023). A spectrum of developmental disorders that includes autism, and Asperger syndrome. "The hub gene Ush2a, whose disruption is associated with both autism spectrum disorders and congenital sensorineural impairment, has itself been found to facilitate vesicle trafficking, consistent with the pathway identity for its EV-enriched module." (PMID 37060018, 2023).
autosomal dominant retinitis pigmentosa (1 paper, 2020). Autosomal dominant retinitis pigmentosa (RP) is an autosomally dominant inherited retinal dystrophy leading to progressive loss of the photoreceptors and retinal pigment epithelium and resulting in blindness usually after several decades. "For patients with autosomal dominant retinitis pigmentosa (RP), the most frequently associated genes were RHO, RP1, and PRPF31; for X-linked and autosomal recessive forms of RP, the most frequently associated genes were RPGR and USH2A, respectively." (PMID 32423767, 2020).
congenital heart disease (1 paper, 2025). A heart disease that is present at birth. "Recent studies also associate USH2A mutations with congenital heart defects." (PMID 40901676, 2025).